CFL1 (cofilin 1)
Diseases named in the same sentence as CFL1 in open-access papers (continued):
Sharing a sentence is not in itself a finding about the gene and the disease.
CFL1 also shares sentences with these, for which no sentence is quoted: Behçet's disease (2 papers); chronic pancreatitis (2); diabetic nephropathy (2); epilepsy (2); lymphoma (2); polymyositis (2); rheumatoid arthritis (2); acute lymphoid leukemia (1); adenoma (1); Allergy (1); aneurysm (1); atherosclerosis (1); autoimmune disorders (1); B cell lymphoma (1); bone disorder (1); brain tumour (1); cardiac disease (1); Cerebral ischemia (1); chronic hepatitis B (1); chronic myeloid leukemia (1); cutaneous melanoma (1); disc degeneration (1); Dyskinesia (1); Ewing sarcoma (1); genetic disorder (1); glaucoma (1); head and neck carcinoma (1); hepatitis C (1); invasive breast carcinoma (1); kidney (1).
A further 20 diseases each share a sentence with CFL1 in 1 paper.